PI3 (peptidase inhibitor 3)
Diseases named in the same sentence as PI3 in open-access papers (continued):
Sharing a sentence is not in itself a finding about the gene and the disease.
cancer (81 papers, 2006 to 2025). A tumor composed of atypical neoplastic, often pleomorphic cells that invade other tissues. "In cancer cells, the expression of four SRGs (PI3, AUP1, CD200 and GNAS) is closely associated with epigenetic regulation and epithelial-mesenchymal signaling." (PMID 40534859, 2025). "GO also listed pathways already known to be linked to Bcl-2 function such as Cell Cycle, MicroRNA in Cancer, Resistance to Drugs, Ras and PI3-Akt Pathways." (PMID 38755629, 2024). "In Network pharmacology analysis, enrichment was linked to the PI3-AKT pathway for both cancer types." (PMID 39687882, 2024). "Essentially, ROS production elevation plays a role in cancer progressions, which are associated with cancer initiation and development through different signaling pathways (PI3/Akt/mTOR, PTEN, MAPK, VEGF/VEGFR, and MMPs)." (PMID 37210478, 2023). "Loss of PTEN function leads to over-activation of the PI3/Akt pathway, which is common in cancer cells." (PMID 31159158, 2019). "We also found few mutations from either cancer set in the PI3_PI4_kinase domain, however, the C-terminal region of the domain is believed to be partially disordered, likely preventing alignment of the domain model to that region." (PMID 22759657, 2012). "We identified hypoxia-inducible factor 1 (HIF 1) pathway, blood vessel development, adipocyte regulation, retinoic acid regulation, hypoxic signaling, associated cytokine pathways, PI3/Akt signaling, and pathways in cancer as pathways that are potentially contributory." (PMID 38099221, 2023). "Moreover, the enrichment of a higher number of target genes in MAK and PI3/Akt signaling pathways indicates the possible modulation of these pathways and, thereby, the associated cancer hallmarks by WA-induced miRNAs." (PMID 36676955, 2022). "Inhibiting cell proliferation, survival, angiogenesis, metastasis, and migration, kaempferol has been demonstrated to modify several molecular mechanisms and pathways, including the PI3/Akt, mTOR, and Erk/MAPK pathways implicated in the advancement of cancer." (PMID 40868987, 2025). "⁃Akt Signaling Pathways: In cancer control and development, Akt/PI3 signaling pathway plays a crucial role." (PMID 36865478, 2023). "Although blockage of autophagy and disruption of lysosome homeostasis is considered as some of the reasons, how inhibition of PI3,5P2 selectively kills cancer cells remains largely elusive." (PMID 37751887, 2023). "Enhanced FAK phosphorylation was reported to activate ERK and PI3, contributing to improvement of the migratory and invasive ability of cancer cells." (PMID 34204745, 2021). "In turn, focal adhesion kinase (FAK) phosphorylation was reported to activate a multitude of protein kinases, such as ERK and PI3, contributing to the improvement of the proliferative, migratory, and invasive ability of different types of cancer cells." (PMID 34204745, 2021). "The tumor suppressive function of FOXOs is supported by existing evidence that FOXOs are either deleted or completely inactivated in various human cancers by the PI3-AKT signaling pathway that is commonly de-regulated in cancer." (PMID 32629884, 2020). "Growing evidences have indicated that the dysfunction of PI3/AKT signaling pathway is one of the hallmarks for human cancers." (PMID 31719796, 2019). "PI3/AKT signaling pathway is a key mechanism for the role of FOXO family members in various cancers." (PMID 31823759, 2019). "SCD or PI3 expression was significantly up‐regulated in cancer tissue compared to that in non‐tumour tissue." (PMID 30592142, 2019). "MAPKs and PI3/AKT pathways both play key role in cancer cells survival and tumor resistance in response to chemotherapeutic drugs." (PMID 28743999, 2017).
cancer (continued). "ATM (ataxia telangiectasia mutated) belongs to the PI3/PI4-kinase family, is able to form a complex with EGFR, causes phosphorylation of AKT and was suggested as a therapeutic target in cancer." (PMID 28199979, 2017). "The genes validated in this study – PTGS2, IL8, IL23A, TACC2 and PI3 – were selected based upon their differential response to treatment and their implication for cancer initiation." (PMID 24848801, 2014). "In vitro screening in MCF-7 human cancer cells showed that the compound induced apoptosis in the cells most probably via PI3/Akt and NF-κB signaling which lead to the activation of the mitochondrial cell death pathway." (PMID 24351905, 2013). "Upon ligand binding, OSMR can activate signaling pathways implicated in cancer such as STAT, PI3/AKT, and mediates inhibition of tumor growth." (PMID 18559093, 2008). "The PI3-Akt pathway is highly active in cancer, and its activation is the core of the most unregulated metabolic pathways and satisfies the biosynthetic needs of rapidly growing cancer cells." (PMID 40901678, 2025). "Furthermore, the expression of QPCTL was positively correlated with SAA1, POSTN, PLA2G2A, SAA2,C6orf15, H19, PI3, etc., whose expression also affects cancer progress." (PMID 37063864, 2023). "However, there is evidence that KDM5B is implicated in numerous pro-oncogenic mechanisms in many different types of cancer, including the hypoxic response, immune evasion and PI3/AKT signalling." (PMID 37152294, 2023). "MMP17, PI3, TLL1, ANGPTL4, and TGFBI have all been previously associated with cancer." (PMID 37388244, 2023). "The functional analysis results from DAVID on all down-stream mRNA targets of the significantly differentially expressed miRNAs suggest that these miRNAs may regulate mRNAs related to cancer and proliferation related pathways such as PI3-Akt, Ras, MAPK." (PMID 31324852, 2019). "The contribution of areca nut extract to autophagy may be explained by ROS generation or hypoxic condition in cancer cells, following the stimulation by various signaling pathways of PI3/AKT, MEK/ERK, AMPK/mTOR, or HIF-1α 63, 65-66." (PMID 31417650, 2019). "The MAPK and PI3-Akt pathways overlap with other pathways, including the cell-cycle and cancer." (PMID 30186694, 2018). "Chemotherapeutic agents, commonly applied in cancer diagnosis and treatment, could inhibit proliferation or induce cancer cell death through various molecular pathways, such as nuclear factor-κB (NF-κB), vascular endothelial growth factors, PI3/Akt and so on." (PMID 34071298, 2021). "Further KEGG analysis showed that DE-ARGs were highly enriched in the PI3-Akt pathway, MAPK pathway, and microRNAs in cancer." (PMID 40901678, 2025). "KEGG analysis showed that key ARGs were highly enriched in the PI3-Akt pathway, MAPK pathway, and microRNAs in cancer." (PMID 40901678, 2025). "In terms of malignancies, it kills cancer and cancer-initiating stem cells via activating AMPK pathway, which has a downstream inhibitory effect on cellular proliferation kinases such as PI3/AKT/mTOR." (PMID 39105978, 2024). "RAS oncoproteins are mainly involved in the PI3/AKT and MAPK/ERK pathways, and their over-activity has been detected in several human cancers, especially BC." (PMID 37511924, 2023). "(c) The PPI network analysis showed enrichment in the key angiogenic pathways, such as the HIF1 pathway, PI3-AKT pathway and cell cycle pathway, critical in angiogenesis and cancer development." (PMID 33803224, 2021). "As recent review reported several pathways in Treg from cancers including Foxp3, IRF4, PI3/AKT/FoxO axis, Helios, Eos, Nr4a, Bach2, E proteins and their inhibitor of DNA-binding (Id) counterparts, STAT3, and NF-kB." (PMID 34084175, 2021). "Previous studies have shown that STS mediates cell death via activation of caspase-3 and the down-regulation of the PI3/Akt and MAPK/Erk pathways, which are important for cancer cell survival." (PMID 32533048, 2020).
cancer (continued). "Leptin exposure increased cancer cell migration/invasion through leptin-mediated activation of JAK/STAT3, PI3/AKT and RhoA/ROCK and promoted new lamellipodial, stress-fiber and focal adhesion formation." (PMID 26053184, 2015). "Furthermore, CHRDL2 was found to differentially impact several key cancer pathways, including the EMT pathway, MYC, MTOR, PI3/AKT and RAF." (PMID 40434957, 2025). "Kaempferol has been proven to alter several molecular mechanisms and pathways, such as the PI3/Akt, mTOR, and Erk/MAPK pathway involved in cancer progression, showing its inhibitory effects on cell proliferation, survival, angiogenesis, metastasis, and migration." (PMID 38730663, 2024). "Similarly, in many cancers YAP/TAZ are overexpressed by upstream oncogenic signaling pathways such as EGFR, RAS-MAPK, PI3, WNT, and exhibit increased YAP nuclear localization." (PMID 36523977, 2022). "Additionally, PIK3CA and PTEN are known regulators of PI3/AKT signaling, which is a key regulatory pathway that can promote cancer growth and proliferation." (PMID 32626534, 2020). "The cellular signaling pathways for each group of genes under MPS1 inhibition, and the top canonical pathways found included: PI3/AKT signaling, Neurogulin signaling, ErbB signaling, GBM signaling, UVB induced MAPK signaling, mTOR signaling and Molecular mechanism of cancer." (PMID 25991676, 2016). "Since the PI3/Akt or MAPK/ERK pathways are responsible for the control of the growth and survival of cancer cells, we wondered whether exosomes are able to induce cancer cell proliferation through the activation of these signaling pathways." (PMID 25644060, 2015). "NF-kB is one of the key proteins that regulate cancer cell proliferation and survival by activating many pro-survival and anti-apoptotic genes, such as BCL-xl and survivin, as well as by interacting with other survival pathways, such as PI3/Akt." (PMID 25644060, 2015). "The PI3/AKT signaling pathway plays vital roles in the regulation of signal transduction, cell proliferation, apoptosis, metabolism, angiogenesis, and other biological processes; it is involved in the cell cycle process of cancer cells and is a potential signaling pathway for tumor treatment." (PMID 37965271, 2023). "NF-κB-induced signaling is a frequent consequence of the upregulation of PI3 and MAP kinase pathways in cancer and has been demonstrated to be a target of CLA in both cancer and non-cancer cells." (PMID 19399184, 2009).
tumor (79 papers, 1997 to 2025). "PTEN is a tumor suppressor which exerts tumor-suppressive functions, mainly by impairing the phosphoinositide 3-kinase (PI3)/AKT/mTOR pathway relevant for cell growth and survival through dephosphorylating the 3- position of phosphoinositides." (PMID 39851496, 2025). "Numerous differentially expressed genes identified from both comparisons are linked to cell proliferation pathways such as PI3/AKT/mTOR and TNF-α, suggesting a tumor-prone or precancerous state in the mammary glands of tumor-bearing mice." (PMID 41387465, 2025). "When migratory tumor cells overlapped with myCAF, they mainly promoted cell migration and adhesion via the PI3-Akt signaling pathway." (PMID 38892065, 2024). "It mediates tumor expansion by activating intracellular PI3/akt, MAPK/ERK, and Jak/STAT signaling pathways." (PMID 39513103, 2024). "Categories of pathways enriched in the primary versus recurrent tumor included immune system function, cell adhesion, and PI3-AKT signaling." (PMID 37457440, 2023). "PI3, also known as elafin, is an elastase-specific inhibitor that directly affects tumour suppression by inhibiting elastase." (PMID 37388244, 2023). "PTEN is a critical tumor suppressor gene related to survival, proliferation, cell migration, and angiogenesis through the PI3/Akt pathway." (PMID 35049697, 2022). "For example, PRDX2 can participate in the regulation of tumor development and oxidative stress in treatment through the PI3/AKT-resistant pathway." (PMID 36141135, 2022). "The GABAB receptor antagonist exhibited anti-tumor effects at the G1/S cell cycle checkpoint and induced apoptosis via dual inhibition of the PI3/Akt/mTOR and MAPK signaling pathways." (PMID 29514603, 2018). "Establishing an inducible knockdown system and performing gene expression arrays we observed an association between IL-16 expression and activation of PI3, NFκB and MAP kinase pathways and, specifically, genes involved in tumor cell proliferation." (PMID 28512269, 2017). "The supression of MIF and PI3/Akt pathway would be certainly involved in tumor suppressive role of miR-451." (PMID 28704499, 2017). "The effects can be reversed by ligand stimulation, which triggers the intrinsic tumor suppressive signaling pathways of EphA2 including inhibition of PI3/Akt and Ras/ERK pathways." (PMID 22916121, 2012). "Previous studies have demonstrated that αvβ3 regulates the expression of Pim-1 and VEGF, and mediates tumor angiogenesis through the PI3/AKT signaling pathways." (PMID 23119061, 2012). "Importantly, all 10 analysed miRs were enriched in the PI3-Akt signalling pathway, which is relevant to tumour progression and endocrine resistance in BC38." (PMID 37491482, 2023). "Palmitic acid shows anti-inflammatory and anti-tumor activity by suppressing the PI3/AKT pathway." (PMID 37007000, 2023). "Furthermore, it has been reported that the NF-ĸB/mTOR and PI3/Akt signaling pathways mediated apoptosis induction in the WA-treated breast TNBC cells." (PMID 36676955, 2022). "Tumor suppressor gene coding for a phosphatase that inactivates the PI3‐AKT pathway." (PMID 33599076, 2021). "Regarding the significance of PI3K signaling pathway in tumor pathogenesis, PI3 gene may also play indispensable roles in carcinogenesis process." (PMID 32076707, 2020). "We next analysed the relationship between SCD/PI3 levels and tumour progression status." (PMID 30592142, 2019). "Despite this, activation of PI3’-lipid signaling remains rate limiting with respect to tumor initiation and growth in KRASG12D-driven lung tumors as evidenced by the strong cooperation between KRASG12D and PIK3CAH1047R in promoting lung tumorigenesis in a GEM model." (PMID 31452510, 2019). "Deregulation of EGFR and c-Met may trigger similar downstream signaling, such as Ras-MAPK and PI3-AKT for tumor progression." (PMID 30577605, 2018).
tumor (continued). "In addition, cleavage of caspase-9/-3 and PARP1 was increased in PI3/SLPI-deficient cells upon TRAIL treatment, substantiating the tumor-protective role of these two peptidase inhibitors through regulation of both intrinsic and extrinsic apoptosis pathways downstream of TSPO." (PMID 37158962, 2023). "Furthermore, Msln stimulated PI3/Akt and MAPK/ERK signaling and inhibits pro-apoptotic factors such as Bad and Bax and causes the tumor cells to survive for longer periods, and at the same time promotes the expression of anti-apoptotic gene such as Bcl-2 and Mcl-1." (PMID 27626699, 2016). "Moreover, S9 induced rapid apoptosis in tumor cell, which might reflect a synergistic cooperation between blockade of both PI3-Akt-mTOR signaling and tubulin cytoskeleton." (PMID 19293927, 2009). "Statistical analysis showed significant tumor-specific upregulation of WFDC1, WFDC2, WFDC3, SLPI, PI3, and ANOS1 (P < 0.0001), while WFIKKN1 was notably downregulated in neoplastic tissues (P < 0.0001)." (PMID 40350979, 2025). "LRP1, AKT2, PI3, IL27RA, OBP2A, and PAEP were found to be more expressed in OC tumour samples than in normal tissues." (PMID 39063239, 2024). "Further multivariate analysis unveiled significant insights: LRP1, PAEP, PI3, OBP2A, and IL27RA genes exhibited higher levels in the tumour group, whereas FOS, PDGFRA, and FGF7 showed higher expression in normal ovarian tissue (all p < 0.001)." (PMID 39063239, 2024). "Our stromal score analysis showed a favourable link between the expressions of genes such as LRP1, FGF7, FOS, PI3, PAEP, and PDGFRA and tumour purity in our investigation of the effect of IRGs on OC’s TME." (PMID 39063239, 2024). "This resulted in the downregulation of the MAPK/ERK and PI3/Akt signaling pathways, decreased cell–ECM interactions and cell migration, and ultimately inhibited tumor progression and potential tumor resistance following treatment." (PMID 37483505, 2023). "Past studies showed that CXCL13, IDO1, PI3, SPP1 and TRIM22 were closely correlated with the prognosis, immunization and chemotherapy sensitivity of tumor." (PMID 34736480, 2021). "Activation of PI3/AKT signaling and tumor microenvironment, and inactivation of semaphorin signaling pathway were observed in A3250 in comparison to both, MDA-MB-231 and IBC3." (PMID 34824220, 2021). "Compared with the paracancerous tissues, the expression of CXCL13(P = 0.0093), IDO1(P = 0.0068), PI3(P = 0.0161), SPP1(P = 0.0122) in tumor tissues was significantly increased, while TRIM22(P = 0.0342) was significantly decreased." (PMID 34736480, 2021). "Since its discovery, AXL has been shown to be involved in a wide range of signaling pathways such as PI3/AKT, MAPK, and SNAIL/EMT, promoting tumor cell survival and proliferation, as well as tumor migration and invasiveness." (PMID 34877810, 2021). "Some tumor-related regulatory pathways were observed, including PD-L1 expression and PD-1 checkpoint pathway, MAPK pathway, PI3–Akt pathway and so on." (PMID 33024415, 2020). "The RAS/MAPK and PI3/AKT signaling pathways are enabled due to RET proto-oncogene activation or NF1 tumor suppressor inactivation, resulting in tumor formation." (PMID 33081307, 2020). "Hypoxia can also contribute to the tumour progression in a HIF-independent manner via the activation of a complex signalling network pathway, including JAK-STAT, RhoA/ROCK, NF-κB and PI3/AKT." (PMID 31835751, 2019). "Since MAP kinase/ERK and PI-3/AKT pathways influence COX-2 stimulating pathway, they are likely to be involved in the mechanism for THC to inhibit tumor growth and tumor progression." (PMID 26881213, 2016).